TLR2 (toll like receptor 2)
Diseases named in the same sentence as TLR2 in open-access papers (continued):
Sharing a sentence is not in itself a finding about the gene and the disease.
infection (continued). "Therefore, we treated DCs with a combination of α-TLR2 and α-TLR4 blocking antibodies prior to infection and monitored subsequent expression of SOCS proteins." (PMID 33023610, 2020). "Therefore, this study demonstrates for the first time that neutrophil activation during F. pedrosoi is conidial or hyphal-specific with TLR-2 and TLR-4 being essential during conidial infection but unnecessary for hyphal killing by neutrophils." (PMID 33193308, 2020). "Meanwhile, we also assume that the decreased level of TLR2 and TLR4 in both spleen and MLNs could be considered as a result from L. salivarius improving intestinal barrier after infection since the pathogens leaked from lumen might be reduced." (PMID 33392276, 2020). "In the case of Δlgt mutant infection in WT mice, no increased metabolic fitness and normal TLR2 mediated immune responses (two ‘good’ effects) led to the milder disease." (PMID 32404866, 2020). "First, we verified an impairment in neutrophil migration to the infection site in animals lacking TLR-2 and TLR-4 in both conidial and hyphal infections." (PMID 33193308, 2020). "Here, we can conclude that PRV-Becker replication is limited in the footpad of TLR2 KO mice and the infection does not spread and replicate in the DRGs." (PMID 31675371, 2019). "Additionally, we evaluate the expression of TLR2 and TLR4 after 24 h of infection and the expression of these receptors was similar to that obtained after 4 h of infection." (PMID 31119102, 2019). "TLR2 has been shown to play a role in host defense against Mtb in several rodent studies but its role in host innate immunity during infection is still not clear." (PMID 31747871, 2019). "These evidences do not exclude that Tlr2 has many other functions during infection such as phagocytosis." (PMID 31747871, 2019). "Infection of murine bone marrow-derived macrophages (BMDMs) with TIGR4 strains demonstrated that macrophage TNF and IL-6 responses to S. pneumoniae were, as expected, highly dependent on TLR2." (PMID 31551336, 2019). "However, TLR2 showed reduced amounts of TLR2 in the cytoplasm of Cav1−/− MDSCs before BCG infection and a failure to increase intracellular TLR2 after infection." (PMID 31849990, 2019). "The anti-HSV response in the presence of TLR2/9 involved increased differentiation of TNF-α- and iNOS-producing DCs (Tip-DCs) and the activation of NK cells, which was accompanied by increased recruitment of the latter to the site of infection." (PMID 31114761, 2019). "After 6 h of infection, the production of IL-6, CXCL1, and CCL2 increased in WT PMCs, but not in Tlr2-deficient PMCs (P < 0.001, for each at MOIs of 0.05 and 0.1)." (PMID 31636643, 2019). "As such, TLR2, TLR3, TLR4, TLR7, TLR8, and TLR9 are known to recognize EBV during infection." (PMID 31238570, 2019). "When compared with the uninfected mice, both the infected TLR2+/+ and infected TLR2-/- mouse groups experienced significantly reduced body weights from 9 days after infection with T. gondii, but no mice died." (PMID 31404078, 2019). "We found that none of the tested strains influenced the macrophages' surface expression and mRNA level of TLR2, regardless of the infection time (0.5–24 hours)." (PMID 31871425, 2019). "Thus, not only do TLR4 and TLR2 mRNA and protein increase in the myometrium at term, but TLR4 null mutant mice are resistant to infection-induced PTB18,19." (PMID 30886179, 2019). "Although we have not evaluated the involvement of other receptors besides TLRs, our data indicate that TLR2 and TLR4 might play essential roles in the modulation of PMN functions by gp43 during an active infection." (PMID 31886295, 2019). "In order to investigate the systemic effects of the tlr2 mutation we compared basal levels of gene expression in the absence of infection between tlr2 homozygote and heterozygote mutants." (PMID 31747871, 2019).
infection (continued). "This may be attributed to the low levels of proinflammatory cytokines induced in TLR2−/− mice, facilitating MRSA colonization and infection." (PMID 31186320, 2019). "The absence of TLR2 and inhibition of let-7e increased the expression of the arginase 1 (Arg1) mRNA but did not alter the protein level during infection." (PMID 30555476, 2018). "MyD88, TLR2, and TLR4 regulated miRNA expression, such as let-7e, during the course of infection." (PMID 30555476, 2018). "Infection of these cells with wildtype HIV-1LAI demonstrates lower infection as compared to the controls, although this effect is not as extreme as for CXCR4 KO (31-fold decreased infection for CXCR4-KO lines in orange, 3-fold for TLR2-KO lines in green)." (PMID 30520725, 2018). "The mycoplasma lipoproteins play a key role in infection and modulate immunity via TLR1 and TLR2." (PMID 30564215, 2018). "However, preclinical studies have shown the potential of combining anti-TLR2 and TLR4 antibodies with antibiotics to reduce inflammation whilst controlling infection." (PMID 30538643, 2018). "In contrast, neither M. leprae infection not TLR2/1 activation of IL-15 MΦ induced upregulation OAS1 as a result of infection or following TLR2/1 stimulation." (PMID 30300363, 2018). "By detecting extracellular T. cruzi through TLR2 and TLR4 at the moment of the infection, or intracellular T. cruzi through TLR9 and TLR7, the cardiomyocytes should activate the MyD88 pathway and induce CCL5 that will focus the recruitment of cytotoxic CD8+ T cells towards the infected cell." (PMID 30067739, 2018). "In terms of TLR9+ expression, we identified stronger interactions with clinical infection by L. (L. ) amazonensis as opposed to the expressions of TLR2+ and 4+, indicated by greater expression in the ADCL/L." (PMID 29543867, 2018). "Surprisingly, the interaction of EFGR and NTHi also results in negative regulation and suppression of the induction of TLR2 via the Src-MKK3/6-p38 α/β MAP kinase-dependent signaling cascade, and this in turn may facilitate NTHi infection." (PMID 30455693, 2018). "TLR2 is an important receptor in NETs formation and SS2 infections." (PMID 30581435, 2018). "TLR2 KO mice showed modest mortality with 30, 30, and 40%, while TLR9 KO mice exhibited apparently enhanced mortality with 55, 60, and 70%, depending on the infection dose." (PMID 29760708, 2018). "Further, we find that TLR2 mediates enhanced infection of THP-1 cells by HIV-1 regardless of viral entry pathway used, as it impacted infection through both the HIV envelope and the VSV-G glycoprotein." (PMID 30520725, 2018). "An OmpA-deficient strain of K. pneumoniae shows increased stimulatory activities in airway cell responses through activation of TLR2-, TLR4-, and NOD1-mediated recognition; accordingly, this mutant is completely excluded from the lung in an animal infection model." (PMID 30153274, 2018). "Also, infected TLR2−/− and AKT-blocked mice showed an increased production of IL-12 p40 and IFN-γ compared with infected WT mice at the early stage during infection." (PMID 28979269, 2017). "Cell population profiles in the TG and spleen of C57BL/6 and TLR2/9−/− mice were analyzed without infection and on the 5th day of HSV-1 infection using flow cytometry." (PMID 28222752, 2017). "The number of NK T cells in the spleen did not change significantly with the infection of WT and TLR2/9−/− animals, although the percentage of NK T cells in infected WT mice was larger than that in the TLR2/9−/− mice." (PMID 28222752, 2017). "In SEA model, during infections, absence of TLR2 leads to enhanced the disease severity and Th1 and diminished Th2 responses." (PMID 29225962, 2017). "In contrast, our in vivo data suggest that TLR2 and TLR9 are not crucial for placental inflammation, since the infection in pregnant TLR2−/− and TLR9−/− mice produced similar results to those found in the infected WT group." (PMID 28819109, 2017).
infection (continued). "In the infection with O. tsutsugamushi TLR2, but not TLR4, is required for the release of TNFα and IL-6 by dendritic cells (DCs) upon pathogen contact." (PMID 28770333, 2017). "Functional Slc11a1 can not only overcome a lack of TLR2, but Slc11a1+Tlr2−/− mice are more resistant to intranasal LVS infection than B6 mice." (PMID 28360906, 2017). "However, at the beginning of the infection, the type I IFN (IFN-α and IFN-β) mRNA levels in the lung of WT mice were higher than those in the infected TLR2/9−/− mice." (PMID 28222752, 2017). "We could thus confirm the presence of bacterial components in the pellet that require infection of donor THP-1 cells with viable bacteria and activate recipient macrophages via TLR2." (PMID 28740179, 2017). "Significantly increased mRNA expression of TLR2 in brain homogenates was observed after mice infected with S. pneumoniae compared with mice treated with PBS; however, infection of mice with S. pneumoniae did not enhance protein expression of TLR2." (PMID 28141831, 2017). "In contrast, DCs from TLR2−/− mice infected with L. braziliensis were more competent in priming naïve CD4+ T cells in vitro, promoting in vivo increases in IFN-γ production and resistance to infection." (PMID 28280488, 2017). "TLR2 and TLR6 play a vital role in the inflammatory response against infections." (PMID 29340029, 2017). "Moreover, the common influence of TLR2 2258 G>A, as well as of the recently studied TLR4 896 A>G, 1196 C>T and TLR9 2848 G>A SNPs on the occurrence of the infection and on congenital cytomegaly development was also estimated." (PMID 28118851, 2017). "In contrast, intracellular WCH-SK2SCV infection only induced up regulation of TLR2 but not any significant cytokines expression after 24 h of infection." (PMID 28083514, 2016). "In addition, the expression levels of TLR1, TLR2, TLR7, and TRAF3 were significantly increased in response to GPV and H9N2 infection." (PMID 27916934, 2016). "A lack of TLR2 does not prevent the eventual resolution of the infection, suggesting that other immune components are important for parasite clearance." (PMID 27716391, 2016). "On the contrary, the peritoneal macrophages isolated from TLR-2 knockout mice of the same strain showed no significant increase in Bcl-2 levels post infection." (PMID 27826299, 2016). "Since Orientia lacks the classical ligands for TLR2/4 stimulation, we speculated that the host DAMP molecule, IL-33 plays a role in modulating inflammation responses in this infection." (PMID 26943125, 2016). "In order to find out the role of TLR-mediated responses in the control of this pathogen, the course of infection of B. microti was analyzed over 3 weeks in wild-type (WT) and TLR knock out (KO) mice including TLR2−/−, TLR4−/−, TLR9−/−, TLR2×4−/− and TLR2×4×9−/−." (PMID 28119856, 2016). "The data presented here indicate a role for TLR2 in controlling infection with either L. major or L. mexicana, as mice lacking this receptor develop more severe disease and increased parasite burdens." (PMID 27716391, 2016). "Though the expression of Msr1 and Marco was induced with infection, no significant changes were observed in tlr2-null macrophages or in the absence of Jmjd3, H3K27me3 demethylase." (PMID 27532872, 2016). "Blockage of TLR2 signaling before infection did not significantly alter L. pneumophila replication, as determined by CFU assay." (PMID 27105429, 2016). "Recently, another study reported that absence of TLR2 impaired ehrlichial elimination and the TLR2-dependent immune response was protective against the infection." (PMID 27381289, 2016). "As the disease kinetics in TLR1−/− or TLR6−/− mice do not match that of TLR2−/− mice, this strongly suggests that the role for TLR2 during infection does not require either TLR1 or TLR6." (PMID 27716391, 2016).
infection (continued). "Infections with mice lacking either TLR1 or TLR6, the known co-receptors for TLR2, did not present with the same disease phenotype as TLR2−/− mice, suggesting that neither is crucial for the TLR2-mediated control of infection with L. major or L. mexicana." (PMID 27716391, 2016). "WT and single TLR2, TLR4 and TLR9 KO mice similarly control infection in liver and spleen." (PMID 28119856, 2016). "Particularly, TLR2 is not an essential molecule for protective immunity to low-dose infection, but TLR2 is an essential molecule for protective immunity to high-dose infection of T. gondii (300 cysts or more)." (PMID 27511368, 2016). "Myd88 and Tlr2 ablation produced pronounced effects over the development of a specific Th1 response, based on the classical IL-12/IFN-γ axis, during the course of the infection." (PMID 27377650, 2016). "Studies utilising TLR9−/− mice infected with L. major showed similar disease kinetics to those reported here with TLR2−/− and TLR4−/− mice, with increased lesion sizes and parasite burdens during the acute phase of infection with eventual control of the disease." (PMID 27716391, 2016). "Expression of TLR2 and IFIT1 was also significantly higher in CL lesions, suggesting that these molecules maybe differentially modulated at the infection site, compared to PBMCs." (PMID 27870860, 2016). "Following infection of TLR2−/−/scid double mutant mice, Lyme arthritis severity was returned to WT control levels, suggesting a role for adaptive immune cells in driving the exacerbated disease severity in TLR2−/− mice." (PMID 27857714, 2016). "Our PCRarray data shows that the infection of GM- and M-BMMs from A/J mice with P. brasiliensis leads to no modulation of TLR2, TLR4, and TLR9 coding genes." (PMID 26543326, 2015). "Taken together, these data provide important insights into the role of TLR-2 signaling in promoting Treg-17 populations without affecting their suppressive properties during inflammation and infections." (PMID 25790134, 2015). "Supporting this, we find infection with live bacteria is required for synergy in mortality during coinfection, as treatment with heat-killed streptococci or TLR2 agonist did not reproduce this effect (Fig EV1H)." (PMID 26265006, 2015). "The alteration in the level of expression of TLR2 and TLR4 may point the role of the innate immune system in the pathogenesis of this infection." (PMID 26622306, 2015). "However, during infection with Ft LVS, activation of TLR2 and the inflammasome significantly boosts this response in an IL-1β-dependent fashion." (PMID 25768794, 2015). "Moreover, it has been shown that TLR-2 and TLR-9 are important for parasite control in the early phases of infection." (PMID 26147698, 2015). "Mouse macrophages that do not produce TNF have impaired Camp mRNA production upon infection or activation of TLR2, when compared to wild-type cells." (PMID 25400920, 2014). "In this model, T-cells lacked TLR2 signaling, indicating that TLR2 signaling on T-cells is important during vaccina infection." (PMID 25250027, 2014). "The ability of TLR2 KO mice to survive a lethal secondary challenge was not surprising given that the T-cell response in B6 and TLR2 KO mice was similar on days 7 and 10 post-inoculation during the primary infection." (PMID 25250027, 2014). "Together, these data indicate that the kinetics and magnitude of the T-cell response in the lung during LVS clpB infection is similar in B6 and TLR2 KO mice suggesting that TLR2 signaling is not required to mount an adaptive immune response to LVS clpB." (PMID 25250027, 2014). "We did not see any significant changes in expression of tlr2 or tlr4 two days post infection with S. Typhimurium ΔmsbB." (PMID 25423082, 2014). "Triggering of macrophages by TLR2- or TLR4-activating bacteria impacts IL-10 secretion by these cells, suggesting a potential relevance of the described mechanism for modulating the course of the immune response during infection." (PMID 24227629, 2014).
infection (continued). "Unlike blood-stage infection, intravenous inoculation of PbA (clone 15cy1) sporozoites has absolute dependence on MyD88-dependent TLR2/4 pathway to develop ECM." (PMID 25157202, 2014). "Since activation of nfkbiz and il6 is not attenuated after infection with a PorB-deficient MC58 strain, signal transduction initiated by TLR2/TLR1 does not seem to play a major role in HIBCPP cells, at least for stimulation of the IκBζ-IL6 axis." (PMID 25347003, 2014). "Although the presence of TLR2/1 on lung CD8+ T cells might play a role in host defense in early COPD, repeated cycles of infection could swing the balance from host defense to inappropriate activation and subsequent tissue damage." (PMID 23374856, 2013). "First, we assessed the impact of the absence of TLR2 or TLR9 on the percentage of TNF-α+ cells during the infection." (PMID 23650544, 2013). "Of note, absence of TLR2 was dispensable for bacterial control during infections with either Mtb H37Rv or 02-171 strains." (PMID 23840651, 2013). "TLR2 (but not TLR4) expression is increased on lung macrophages in a mouse model of infection-induced neutrophilic allergic airway disease." (PMID 23606791, 2013). "In addition, we noted upregulation of Toll-like receptors (TLR-2 and TLR-4) as early as 2 weeks that persisted until 12 weeks post-infection." (PMID 23448601, 2013). "Overall, these observations of increased recruitment of inflammatory cells to the lungs in the absence of TLR2 are consistent with the severe inflammatory lung pathology in TLR2KO mice during late stages of infection." (PMID 23785280, 2013). "To interrogate which PRR is essential for mycobacteria-induced MCP-2/CCL8 production in macrophages, we compared mRNA levels of mcp-2/ccl8 among macrophages from wild-type, TLR2−/−, TLR3−/− or TLR4−/− mice after infection with either BCG or H37Rv at an MOI 5 for 24 h." (PMID 23418602, 2013). "Yeast (Candida albicans) and bacterial (Gram negative and positive organisms and their products) infections act as agonists for TLR2/4/5 in vaginal and skin explants and also induce TNFα production." (PMID 24278768, 2013). "Similarly TLR2 signaling in these mice is required to protect and repair IEC barrier function during infection." (PMID 23950714, 2013). "In contrast to the response in the immune cells, the expression of TLR15 was the highest after 24 h of infection (11-fold, p < 0.001), whereas TLR1 and TLR2 expression remained unchanged or was even slightly down-regulated, correlating to the results observed in chicken macrophages." (PMID 24134665, 2013). "Concerning TLR2, the expression of this receptor was not significantly affected in F4/80+CD11b+ and F4/80lowCD11b+ cells in the early phase of infection." (PMID 23650544, 2013). "Infection of mice with as few as 102 CFU resulted in increased mortality in CD14−/− and TLR2−/− mice, though only the latter reached statistical significance wherein the MTD was 18 days versus >21 and the percentage surviving was 50% versus 100% for control animals." (PMID 23554897, 2013). "The absence of TLR-2 reduced by 62% the increase of H-ferritin after 24h of infection and as much as 83% after 4 days." (PMID 24349383, 2013). "Our study demonstrates that, during Mtb infection, TLR2 signaling on Tregs does not significantly contribute to the expansion and recruitment of Tregs to sites of infection." (PMID 23785280, 2013). "Since RSV activates TLR signaling (via TLR2 and TLR4) during infection, we next investigated whether TLR/MyD88 pathway is required for IL-1β secretion during RSV infection." (PMID 22295065, 2012). "The results of this assay suggested TLR2 was differentially expressed in males and females at day 3 post infection, with females having greater expression of TLR2 compared to males; data not shown." (PMID 23241283, 2012). "Antibody detection reveals that TLR2 and 4 are required to generate early antigen-specific IgG, but not during the late stages of infection." (PMID 22973560, 2012).